AXL (AXL receptor tyrosine kinase)
Diseases named in the same sentence as AXL in open-access papers (continued):
Sharing a sentence is not in itself a finding about the gene and the disease.
tumor (continued). "AXL is widely synthesized by endothelial cells and could promote angiogenesis by regulating the production of VEGF and PDGF, thus participating in the mediation of normal and tumor vascular systems." (PMID 37265798, 2023). "Despite the fact that AXL itself is not regarded to be a very strong oncogenic driver, overexpression of AXL has been shown to promote tumour cell growth, survival, invasion, metastasis, angiogenesis, epithelial to mesenchymal transition, and immune suppression." (PMID 36620544, 2022). "Notably, the AXL antibody had no anti-tumor activity on its own, requiring the cytotoxic drug to exert an effect." (PMID 35513054, 2022). "Intriguingly, bemcentinib did not appear to uniformly affect the EMT program in this condition, suggesting that the observed immune sensitization of tumor cells relied on alterations in AXL signaling, rather than solely on alterations of the mesenchymal phenotype in this model." (PMID 35572601, 2022). "Neither AXL-CAR T cells nor MWA monotherapy was able to suppress tumour growth." (PMID 36261437, 2022). "However, both MWA and combination therapy failed to suppress HCC827 (AXL negative) established tumour." (PMID 36261437, 2022). "In addition, AXL activation may promote immune suppression through SOC1/3 signaling, enabling tumor evasion." (PMID 34877810, 2021). "After co-implantation with HCC cells in xenograft nude mice and patient-derived xenograft (PDX) nude mice, HUVECs overexpressing AXL could significantly enhance tumor growth, liver metastasis, and vessel metastasis of HCC, which could be abolished by R428, an AXL inhibitor." (PMID 34123800, 2021). "Due to the low percentage of cases with tumor cells with positive immunoreaction for RIPK3, the ROC and AUC for this marker have not been calculated, while for AXL, an exploratory cutoff of 27.5% of positive tumor cells has been calculated with the Youden criteria." (PMID 34745951, 2021). "However, AXL expression in tumor cells was not correlated with OS (p = 0.683) and DFS (p = 0.842) in these patients." (PMID 34123800, 2021). "The presence of these AXL-positive cells was not restricted to tumor-derived cell lines harboring EGFR-oncogenic mutations, as we observed that a similar percentage of AXL-positive cells were present also in cell lines driven for example by mutant KRAS (i.e., A549)." (PMID 34254585, 2021). "Furthermore, AXL was co-expressed with CD31, both in human HCC tumor tissue and peritumor tissues." (PMID 34123800, 2021). "Thus, in at least some cases agents that target both AXL and MERTK may provide better tumor growth control than more selective compounds." (PMID 34830794, 2021). "Both MERTK and AXL are expressed in a wide variety of human cancers, including NSCLC, melanoma, leukemia, breast, colon, liver, gastric, prostate, ovarian, and brain cancers, where they promote tumor cell survival and/or proliferation and contribute to oncogenesis." (PMID 34830794, 2021). "Furthermore, combining pharmacological inhibition of AXL with anti-PD-1 in a preclinical model of breast cancer reduces the primary tumor and metastatic burden, which is not shown when only one of them is treated." (PMID 34778071, 2021). "To investigate whether AXL and c-ABL expression levels are linked to clinicopathological features in EAC, we analyzed our data that included AXL and c-ABL protein expression in tumor samples and their corresponding clinicopathological information from 53 EAC patients." (PMID 32922529, 2020). "Furthermore, high AXL and p-AXL levels in the AXL-high clone strongly induced the tumourigenicity of H1299 cells in SCID/Beige mice, and oral administration of EGCG + GTE inhibited the tumour growth of H1299 cells by reducing p-AXL, SLUG and ALDH1A1 levels." (PMID 32051483, 2020). "Finally, a partial reversal of tumor EMT with TGFβ-, AXL- and YAP-targeting therapies may re-sensitize tumors to immunotherapies by restoring antigen expression and allowing tumor T-cell infiltration." (PMID 32992658, 2020).
tumor (continued). "Notably, tumours of the EGCG + GTE group had lower levels of p-AXL and AXL compared with those of the non-treated group." (PMID 32051483, 2020). "However, regardless of AXL expression, a small population of tumor cells survived even after 72 h of exposure to 1 μmol/L osimertinib, suggesting osimertinib tolerance in these populations." (PMID 32929081, 2020). "Uncoupling of PEAK1 from AXL signaling decreases metastasis in vivo, but not tumor growth." (PMID 32681075, 2020). "Moreover, cabozantinib promotes tumor-immune suppression targeting TYRO3, MER, and AXL." (PMID 33194654, 2020). "Interestingly, AXL and vimentin expression also correlated in normal mammary tissue samples from patients, not just in tumor tissue." (PMID 32148495, 2020). "Therefore, targeting both AXL and MERTK kinases may directly impact tumor growth and relieve immunosuppression." (PMID 33425754, 2020). "Mechanistically, we identified that this hMENA‐mediated pro‐tumor function is attributable to its ability to regulate growth arrest‐specific 6 (GAS6) in CAFs and AXL in tumor cells, sustaining the pro‐tumoral paracrine GAS6‐AXL axis, described as crucial in EMT, drug resistance, and immune evasion." (PMID 32909687, 2020). "Indeed, over-expression of AXL may counteract the PTBP1-mediated apoptosis and knockdown of PTBP1 expression may increase tumor growth in vivo." (PMID 31729427, 2019). "Besides that, the expression level of proteins which are utilized by ZIKV for viral entry and replication such as AXL and MSI1 in tumor cells may affect the efficacy of the OV therapy." (PMID 31824472, 2019). "Among three TAM member, AXL, both growth arrest-specific gene 6 (GAS6)-dependent and (GAS6)-independent, can promote many downstream signaling pathways and transcription factors regulating cell survival, growth, EMT, metastasis, and tumor microenvironment in cancer cells." (PMID 31043587, 2019). "Herein, we evaluate the neurotropism of ZIKV relative to the receptor tyrosine kinase AXL and its ligand Gas6 in viral entry and the RNA-binding protein Musashi-1 (MSI1) in replication which are also overexpressed in GBM, suggesting its potential for specific targeting of the tumor." (PMID 31824472, 2019). "However, we have shown that the concentrations of AXL and GAS6 in plasma were not correlated with the corresponding expression levels in tumor tissue of NSCLC patients harboring EGFR activating mutations." (PMID 31419057, 2019). "In the subgroup of patients with NSCLC with brain metastases, the high expression of AXL (AXLHigh) was significantly associated with GAS6 expression (P < 0.001), but not with tumor differentiation, gender, age, smoking history, pathology, T stage, N stage, CEA, and LDH (all P > 0.05)." (PMID 28551766, 2017). "To investigate whether validated targets of miR-34a were modulated by its synthetic mimic in DMPM cells, we assessed protein expression levels of c-MET, AXL, and CDK6 considering their established role in the control of cell proliferation and apoptosis in different tumor types." (PMID 28100259, 2017). "Inhibitors of signaling specific to reciprocally engaged tumor cells, such as or AKT or IGF1R/AXL, block heterocellular phenotypes (e.g., protein expression, proliferation, mitochondrial performance, and anti-apoptosis), but have little effect on KRASG12D tumor cells alone." (PMID 27087446, 2016). "EGFR, PTEN, cMET and AXL expression did not correlate with tumor response." (PMID 27028852, 2016). "Interestingly, in our patients, 90.5 % of betel nut chewers were positive for AXL in tumor tissue, which was significantly higher than in non-chewers (P=0.029, data not shown)." (PMID 27172793, 2016). "Irrespective of downstream signaling, shRNA-mediated AXL knockdown significantly diminished the tumor-forming capacities of Lipo-246 and Lipo-863 cells in vivo, a finding that indicates that AXL may represent a molecular target in a subset of DDLPS tumors." (PMID 26573603, 2015).
tumor (continued). "However, our results, when combined with previous findings, indicate that AXL may contribute to tumor aggressiveness in DDLPS and PLS and that further studies are warranted to determine the utility of AXL as a potential molecular prognosticator for LPS." (PMID 26573603, 2015). "Finally, we employed a humanized AXL monoclonal antibody developed by our group and showed that specific inhibition of AXL could attenuate TNBC cell proliferation and cell migration in vitro and tumor formation in mice." (PMID 26356563, 2015). "To determine whether overexpression of AXL in cultured DDLPS and PLS cell lines is an accurate representation of the human disease, we performed IHC analyses of two TMAs by comparing WDLPS, DDLPS, and PLS patient tumor samples to NF controls." (PMID 26573603, 2015). "Thus the inter-cellular interactions of AXL, FN14, and ADAM9 may be important in regulation of coupling between tumor and stromal cells." (PMID 22570691, 2012). "In addition, AXL may signal through NF-κB and matrix metalloprotease 9 (MMP 9) to drive tumor invasion." (PMID 23077658, 2012). "AXL may contribute to an immune-evasive TME by impairing antigen presentation, increasing PD-L1 expression on cancer cells, enabling intrinsic cancer cell-resistance to immune-mediated killing, and altering the cytokine profile in the TME to be more tumor-supportive." (PMID 39238637, 2024). "Additionally, the AXL-Fc competition assay confirmed that the AXL54-x-CD3 Pronectin is specifically targeting the AXL receptors on the tumor cells because the AXL-Fc protein was able to bind to AXL54-x-CD3 and neutralize the bispecific molecule, prevent its binding to the tumor cells." (PMID 36551940, 2022). "Thus, AXL should not be generalized or categorized as a tumor-specific marker." (PMID 35572601, 2022). "Interestingly, we also compared their expression levels between tumor and normal tissues and found that the expressional changes were complex, especially significantly upregulated genes (CDKN2A, MYCN, PLK1, and TERT) and some downregulated signatures (AXL, ID1, and TLR3)." (PMID 35754848, 2022). "However, CM of HUVECs overexpressing AXL could enhance the migration of HCC cells, but showed no obvious effect on the proliferation of HCC cells, which indicates the important ability of AXL in TECs on HCC metastasis, but the limited activity of AXL on HCC tumor growth." (PMID 34123800, 2021). "Furthermore, AXL has been shown to suppress antigen presentation by downregulating major histocompatibility complex I (MHC-I), and genetic ablation of AXL in the experimental PyMT-induced tumor model was shown to induce MHC-I expression to even higher levels compared to IFN-γ-induced parental cells." (PMID 35582229, 2020). "IHC of xenograft tissues revealed inhibited MET and AXL activation; however, in vivo tumor cell proliferation or apoptosis was not affected by LY2801653 (data not shown), which was in accordance with our in vitro results, suggesting the antitumor mechanism might be related to tumor microenvironment." (PMID 34766112, 2020). "As AXL was minimally expressed in the ADRN subtype, we did not observe any correlations between AXL expression and tumor/immune cell fraction in ADRN-dominant samples." (PMID 39825754, 2025). "AXL also forms a complex with the non-receptor tyrosine kinase SRC and mediates the enhanced activity of MET in an HGF-independent manner to facilitate tumor migration and invasion in ccRCC." (PMID 36831657, 2023). "SRC proto-oncogene nonreceptor tyrosine kinase is a direct target of GAS6/AXL signaling, and once activated, it induces the MET proto-oncogene, thereby regulating EMT and ccRCC tumor metastasis." (PMID 35659268, 2022). "This tumor subpopulation is characterized by high expression levels of the RTK NGFR but, unexpectedly, not AXL." (PMID 32770055, 2020).
tumor (continued). "Our results are well supported by evidence that the p-AXL levels in tumours of the EGCG + GTE group were strongly reduced by 0.36-fold compared with those of the non-treated group, whereas AXL levels in tumours from both groups were nearly the same." (PMID 32051483, 2020). "Collectively, these results demonstrate that the AXL/PEAK1 signaling complex is essential for the cell migration/invasion and FA turnover that lead to metastasis, yet this complex is not required for tumor growth." (PMID 32681075, 2020). "Since most tumor cells overexpress AXL, a tyrosine kinase receptor with oncogenic functions, an RNA aptamer against AXL, GL21.T, has been developed and used to block AXL downstream signaling 18 and to selectively deliver small non-coding RNAs 19-21." (PMID 32174798, 2020). "To investigate the effect of AXL knockdown on both MPNST tumor growth in vivo, we subcutaneously injected MPNST724 cells harboring shNT (non-targeting control), AXL sh1, or AXL sh2 into hairless SCID mice." (PMID 33283192, 2020). "From these findings, additionally targeting the AXL appears to be a rational approach to overcome EGFR resistance, since HER2/HER3 signaling inhibition is not sufficient for complete tumor suppression." (PMID 30700700, 2019). "For example, an engineered AXL decoy receptor, which antagonizes the GAS6/AXL system by capturing GAS6, can inhibit cancer cells and tumor growth without toxicity." (PMID 31043587, 2019). "Expression levels of AXL and GAS6 were different in two major tumor size groups, although not statistically significant (P=0.7)." (PMID 31700829, 2019). "Among other targetable tyrosine kinases AXL, MET and EGFR were expressed at high levels in some, but not all, tumor samples." (PMID 30881919, 2019). "The lack of changes to AXL and tubulin stability suggested the existence of other mechanisms by which RARRES1 acts as a tumor suppressor in TNBC." (PMID 27286452, 2016). "Even though the increase from normal to primary tumor tissue was non-significant, AXL expression further increased significantly in lymph node metastases and local recurrences, extending previous studies regarding HNSCC tumor progression." (PMID 28025482, 2016). "We did observe a negative correlation between AXL expression and tumor fraction in MES-dominant samples (cor = −0.5; P = 6.85e-3), though the MES-dominant samples with the highest tumor purity still expressed AXL at higher levels than ADRN-dominant samples." (PMID 39825754, 2025). "Interestingly, AXL KO did not affect CIN levels, suggesting a potential role in tolerating increased CIN, such as that present during tumor progression." (PMID 37809421, 2023). "In addition, it did not alter tumor invasion, indicating that AVB-500’s inhibitory effect is specific to AXL." (PMID 36980768, 2023). "Bioluminescence imaging (BLI) demonstrated that AXL-CAR T cells partially suppressed the pulmonary tumour in the majority of mice on day 38, whereas CD19-CAR T or PBS could not control tumour progression." (PMID 36261437, 2022). "Interestingly, PCI37A-AXLC2 cells did not express more NRG1 compared to vector control despite AXL being overexpressed, and cetuximab-resistant PDX tumor (UW-SCC25) did not express NRG1 even though they had AXL expression." (PMID 35461210, 2022). "Furthermore, the patients with AXL expression in TECs had lower OS (p = 0.048), but not DFS (p = 0.893), compared with the patients with AXL expression in tumor cells." (PMID 34123800, 2021). "However, detailed parts are still to be further demonstrated because the number of tumor-infiltrating CD8+ T-cells is increased after AXL inhibition, while the other research showed that AXL inhibition does not affect the number of them." (PMID 34778071, 2021). "Although persistent AXL/GAS6 co-overexpression and acquired MERTK and KDR overexpression did not accelerate tumor xenograft growth rate, other concurrent phenotypic changes might nonetheless bear on disease progression." (PMID 34292953, 2021).
tumor (continued). "Moreover, LY2801653 did not directly eradicate tumor cells that moderately express MET and AXL, but act on tumor microenvironment." (PMID 34766112, 2020). "However, high expression of AXL in the tumor cells of HCC patients did not affect OS and DFS, compared with patients with low AXL expression in tumor cells, which indicates that AXL expression in TECs played a crucial role in promoting tumor progression and metastasis." (PMID 34123800, 2021). "Furthermore, our studies represent that AXL/EZH2/TGF-β1, but not Sox2, might play a pivotal role in tumor invasion, migration and EMT." (PMID 29642503, 2018).